MIR1302-5 (microRNA 1302-5)
Synonyms: hsa-mir-1302-5; MIRN1302-5
Gene: MicroRNA gene on chromosome 20 (50,614,636 to 50,614,785, reverse strand). Ensembl gene ENSG00000221091.
Gene Ontology:
Biological process: miRNA-mediated post-transcriptional gene silencing